TK1 (thymidine kinase 1)
Diseases named in the same sentence as TK1 in open-access papers (continued):
Sharing a sentence is not in itself a finding about the gene and the disease.
Bladder Urothelial Carcinoma (3 papers, 2023 to 2025). "Additionally, ALYREF contributes to the malignancy of urothelial carcinoma of the bladder (UCB) by maintaining the stability of RABL6 and TK1 mRNA30." (PMID 38491127, 2024).
breast invasive carcinoma (3 papers, 2017 to 2022). "We found that TK1 presented with frequent structural variants, and copy number amplification indicated enhanced TK1 expression in diverse tumors, including breast invasive carcinoma, liver hepatocellular carcinoma, ovarian serous cystadenocarcinoma, uterine corpus endometrial carcinoma, and SKCM." (PMID 35311151, 2022).
breast tumors (3 papers, 2012 to 2018). "Overall, it appears that TK1 has diagnostic and prognostic potential in identifying breast tumor tissue as well as precancerous tissues." (PMID 22778736, 2012). "We also report that TK1 gene expression levels are significantly higher in TNBC vs. HER2+ breast tumors, suggesting TK1 as an alternative biomarker and potential target for TNBC." (PMID 30214377, 2018). "We further detect transcripts of ALDOA and several hub genes in breast tumors by RT-qPCR, and Pearson’s correlation analysis demonstrated a positive relationship of ALDOA with CCNB2 and CDC45, but not CDC20 and TK1, even a trend observed between them." (PMID 28191039, 2017).
cervical carcinoma (3 papers, 2013 to 2022). A carcinoma arising from either the exocervical squamous epithelium or the endocervical glandular epithelium. "Nuclear TK1 expression is also a prognostic factor for treatment outcome, particularly in patients with advanced cervical carcinomas." (PMID 23693054, 2013). "Furthermore, since nuclear TK1 expression is correlated with advanced stage of invasive cervical carcinomas (pathological stage III/FIGO stage IIA – IV), a low TK1 LI can help to identify with a better survival." (PMID 23693054, 2013). "In this study investigating on the expression of TK1 in pre-malignant and malignant neoplasms of the cervix, TK1 LI was found to be a more reliable prognostic marker for 5-year survival than pathological stages, FIGO stages and Ki-67, as demonstrated by LI and 5-year survival data." (PMID 23693054, 2013). "Studies have shown that RRM2, TK1, and TYMS in cervical cancer tissues are significantly different from healthy tissues and are significantly correlated with overall survival in cervical cancer." (PMID 35082972, 2022). "An important observation in this study is that the TK1 intensity (TK1 synthesis rate) increases from CIN grade I to CIN grade III, but does not further increase in invasive cervical carcinomas." (PMID 23693054, 2013).
esophageal squamous cell carcinoma (3 papers, 2021 to 2022). Esophageal squamous cell carcinoma (ESCC) is a type of esophageal carcinoma (EC) that can affect any part of the esophagus, but is usually located in the upper or middle third. "Compared with thymidine kinase 1 (TK1), a key enzyme in cell proliferation, miR-30d-5p had a higher sensitivity and specificity to the abnormal proliferation of esophageal squamous cell carcinoma cells." (PMID 35155437, 2022). "In esophageal squamous cell carcinoma (ESCC), LncRNA CCAT2 increases IGF2BP2 expression, and then IGF2BP2 improves mRNA stability of thymidine kinase 1 (TK1) in m6A modification manner, which promotes tumor progression." (PMID 35541906, 2022).
lymph node metastasis (3 papers, 2020 to 2024). "TK1 was also related to clinical stage, histologic grade and lymph node metastasis." (PMID 38480789, 2024).
non-Hodgkin lymphoma (3 papers, 2007 to 2021). Distinct from Hodgkin lymphoma both morphologically and biologically, non-Hodgkin lymphoma (NHL) is characterized by the absence of Reed-Sternberg cells, can occur at any age, and usually presents as a localized or generalized lymphadenopathy associated with fever and weight loss. "TK1 is traditionally measured by its enzymatic activity and used clinically in non-Hodgkin lymphoma (NHL) but has been documented in few studies on Hodgkin lymphoma (HL)." (PMID 34471484, 2021).
prostate tumor (3 papers, 2022 to 2023). "Data from TCGA databases suggested that SNHG4 expression was significantly correlated with the expression of RRM2, EZH2, AURKA and TK1 in prostate tumor samples (p < 0.01)." (PMID 37596700, 2023). "The expression of TK1 in prostate tumors was significantly elevated in Treg cells and decreased in B cells and activated dendritic cells compared with normal tissues (all p < 0.05)." (PMID 35559045, 2022).
T-cell lymphoma (3 papers, 2018 to 2024). "For example, B-cell lymphoma may exhibit higher levels of IL-10 and TK1 than T-cell lymphoma, while T-cell lymphoma may show higher levels of IL-6." (PMID 39682357, 2024).
adenosis (2 papers, 2012 to 2020). "Using a progressive breast tissue array, precancerous tissue including breast adenosis, simple hyperplasia, and atypical hyperplasia stained positive for TK1 expression." (PMID 22778736, 2012). "Findings of this study showed that 22% of the adenosis samples were positive for TK1, with the earliest indications of increased TK1 levels in sclerosing adenosis—results signifying that TK1 levels could be an early indicator of tumor development." (PMID 33292474, 2020).
clear cell renal carcinoma (2 papers, 2020 to 2023). A malignant epithelial neoplasm of the kidney characterized by the presence of lipid-containing clear cells within a vascular network. "Our study is the first one in the literature that investigated the serum levels of TK-1 in patients with early stages of clear cell renal carcinoma." (PMID 33375435, 2020).
cutaneous melanoma (2 papers, 2022 to 2025). A primary melanoma arising from atypical melanocytes in the skin. "TK1 drives the malignant progression of skin melanoma and metabolic reprogramming." (PMID 39803822, 2025). "Moreover, TK1 expression was higher in advanced patients than that in those with early cutaneous melanoma (p < 0.05)." (PMID 35311151, 2022). "However, the role of TK1 in skin cutaneous melanoma (SKCM) remains unclear." (PMID 35311151, 2022).
diffuse large B-cell lymphoma (2 papers, 2023 to 2025). "The aim was to explore the effect of rituximab in combination with chemotherapy in treating diffuse large B-cell lymphoma and levels of vascular endothelial growth factor (VEGF), thymidine kinase 1(TK1) with interleukin-6 (IL-6), plasma T cells, NK cells as well as B cells." (PMID 40837360, 2025).
metastatic colorectal cancer (2 papers, 2015 to 2019). "Indeed, recent studies discussed the importance of the TK1 expression level as a predictive factor of FTD/TPI efficacy in metastatic colorectal cancer patients." (PMID 31138881, 2019).
metastatic disease (2 papers, 2016 to 2017). "Furthermore, TK1 activity and TK protein levels were increased in patients with lymph node involvement and metastatic disease compared to those without such complications." (PMID 27079872, 2016).
metastatic prostate carcinoma (2 papers, 2024 to 2025). A carcinoma that arises from the prostate gland and has spread to other anatomic sites. "We found that for patients with metastatic prostate cancer, high levels of a protein called TK1 that is involved in cell division was linked to higher risk of death." (PMID 39525979, 2024).
neuroblastoma (2 papers, 2015 to 2023). Neuroblastoma (NB) is the most common solid, extracranial childhood tumor. "Many of these, e.g. NME1, PYCR1, TK1, BIRC5 and TOP2A, are located on Chr 17q, are upregulated in unfavorable neuroblastoma and associated with poor patient outcome." (PMID 37246217, 2023). "We evaluated the effect of palbociclib on the Rb/E2F pathway in neuroblastoma cells by measuring the mRNA expression levels of direct E2F target genes, topoisomerase 2A (TOP2A), cyclin E2 (CCNE2), and thymidine kinase (TK1)." (PMID 26225123, 2015).
ovarian serous adenocarcinoma (2 papers, 2020 to 2023). An adenocarcinoma that arises from the ovary and is characterized by the presence of malignant epithelial cells that, in well differentiated tumors, resemble the epithelium of the fallopian tube or, in poorly differentiated tumors, show anaplastic features and marked nuclear atypia. "Western blotting with TK1-positive/negative cell lysates and IHC of normal tonsil tissue and patients with ovarian serous adenocarcinoma tissue further confirmed the binding of hTK1-IgY-rmAb#5 to native TK1." (PMID 36969497, 2023).
ovarian tumor (2 papers, 2023). "Elevated TK1 protein levels were found in both benign and ovarian tumor (borderline and malignant ovarian cancer) patients." (PMID 36900385, 2023).
viral infections (2 papers, 2022 to 2023). "Furthermore, a few viral infections in humans, mainly caused by the family Herpesviridae (e.g., herpes simplex virus, Epstein‐Barr virus, varicella‐zoster virus and cytomegalovirus) and hepatotropic viruses, are associated with the increased activity of serum TK1." (PMID 36495211, 2023). "Highly complex forms of TK1 have been observed in sera from healthy and subjects with viral infections and malignant diseases [13, 19 and 21]." (PMID 36201558, 2022). "Interpreting the course of TK1 activity rather than a single measurement might also allow the differentiation from inflammation or viral infection, as it should return to normal limits as soon as the inflammation/infection has ceased and it should remain elevated in real neoplasia cases." (PMID 36495211, 2023).
abdominal aortic aneurysm (1 paper, 2024). Enlargement and ballooning of the vessel that supplies arterial blood to the abdomen, pelvis and legs. "Existing studies have shown that NETs promote the proliferation of vascular smooth muscle cells through the Hippo-YAP pathway and Akt/CDKN1b/TK1 pathway in abdominal aortic aneurysm and hypertension, respectively." (PMID 38664728, 2024).
adenoma (1 paper, 2012). A neoplasm arising from the epithelium. "Interestingly, homozygous deletion of Shmt1 did not impact adenoma formation in ApcMin mice since there was a compensatory increase in thymidylate kinase (TK1) expression: a salvage pathway for thymidine synthesis." (PMID 22438825, 2012).
benign colorectal tumors (1 paper, 2020). "A meta-analysis revealed that serum TK1 significantly distinguished healthy persons and those with benign colorectal tumors from patients with CRC (p<0.000001)." (PMID 33247667, 2020).
brain tumors (1 paper, 2021). "Kinetics modelling evidences suggest that in brain tumors, [18F]FLT uptake is tightly dependent on factors related to influx (BBB integrity, permeability and transport expression) and not only to thymidine kinase-1 activity." (PMID 34012924, 2021).
cerebral malaria (1 paper, 2018). A sequestration of Plasmodium falciparum in the brain, which can cause coma and/or seizures. "Thymidine kinase 1 was recently found to be a biomarker of cerebral malaria susceptibility in the murine model, and carbonic anhydrase, reflects the blood’s abnormal acid base environment during severe disease." (PMID 29642892, 2018).
cervical intraepithelial neoplasia (1 paper, 2013). "TK1 expression was determined by immunohistochemistry in cervical lesions (cervical intraepithelial neoplasia (CIN), n = 216; invasive cervical carcinoma, n = 84)." (PMID 23693054, 2013).
colorectal adenocarcinoma (1 paper, 2018). The most common type of colorectal carcinoma. "There was some overlap in TK1 expression in colorectal adenocarcinoma patients vs. normal patients, probably due to the highly proliferative nature of the colon, as TK1 levels rise during proliferation." (PMID 30214377, 2018). "However, TK1 levels in colorectal adenocarcinoma patients are still more upregulated than in healthy normal patients." (PMID 30214377, 2018).
COVID-19 (1 paper, 2024). A disease caused by infection with severe acute respiratory syndrome coronavirus 2. "Among these 10 shared SNPs, rs144204502 was found to colocalize between LTL and COVID-19 susceptibility (PP.H4 = 0.66), which is located near TK1 and encodes a cytosolic enzyme that catalyzes the addition of a gamma-phosphate group to thymidine." (PMID 38882679, 2024).
eczema (1 paper, 2022). "The mechanisms behind the prevention of eczema following probiotics stem from the hygiene hypothesis, where early exposure to gut microbes directs the immune system away from a Th-2 skew or upregulates Tk1-cytokine production." (PMID 36299694, 2022).
endometriosis (1 paper, 2024). The growth of functional endometrial tissue in anatomic sites outside the uterine body. "Interestingly, endometriosis-associated gene dysregulation in early secretory phase matches dysregulation in the transgenic mouse endometrium in the present study in terms of affected gene-set, above all the progesterone-regulated genes (e.g. Errfi1, Bcl6, Cited2, Irs2, Tgfb2, Gpx3, Tk1)." (PMID 38346980, 2024).
glioblastoma (1 paper, 2023). The most malignant astrocytic tumor (WHO grade IV). "In UALCAN, the protein expression of TK1 was evaluated in 10 normal tissues and 99 glioblastoma proteomic profiles from CPTAC." (PMID 36831773, 2023). "TK1 protein levels were also elevated in glioblastoma tissue compared with normal tissue." (PMID 36831773, 2023).
head and neck cancer (1 paper, 2025). A primary or metastatic malignant neoplasm affecting the head and neck. "Kaplan–Meier analysis showed that high TK1 expression correlated with poor overall survival in head and neck cancer." (PMID 40564887, 2025).
head and neck squamous cell carcinoma (1 paper, 2025). A squamous cell carcinoma that arises from any of the following anatomic sites: lip and oral cavity, nasal cavity, paranasal sinuses, pharynx, larynx, and salivary glands. "Among these, thymidine kinase 1 (TK1) emerged as a particularly promising candidate due to its consistent overexpression across datasets and significant correlation with poor survival in stage II–III head and neck squamous cell carcinoma (HNSC) patients." (PMID 40564887, 2025). "In addition, TK1 has been evaluated as a marker of tumor proliferation, primarily through immunohistochemistry and functional imaging using 18F-fluorothymidine (18F-FLT) positron emission tomography (PET) in head and neck squamous cell carcinoma (HNSCC)." (PMID 40564887, 2025).
Hepatitis (1 paper, 2024). Inflammation of the liver. "A screening study of serum TK1 activity, comprising 11,880 individuals, revealed that 83 % of those having a TK1 activity level above the cut-off for healthy individuals had different diseases, from hepatitis to malignant cancers." (PMID 39006942, 2024).
hepatitis B (1 paper, 2021). "L-FMAU, an anti-hepatitis B viral drug, was also phosphorylated at a relative high activity, similar to human TK1." (PMID 34579716, 2021).
infiltrating ductal carcinoma (1 paper, 2018). "In breast tissue arrays, infiltrating ductal carcinoma positive for TK1 has a significantly lower average gray value than normal breast tissue stained for TK1." (PMID 30214377, 2018).
invasive carcinoma (1 paper, 2013). A carcinoma that is not confined to the epithelium, and has spread to the surrounding stroma. "The ratio between the TK1 expression in the cytoplasmic and nuclear group and the total TK1 group increased from CIN grade I to grade III (I = 0.42, II= 0.61, III= 0.67), but did not increase further in the invasive carcinoma pathological stages II and III (II = 0.63, III = 0.66)." (PMID 23693054, 2013).
leukopenia (1 paper, 2018). "TK1 activity may be influenced by certain chemotherapeutic agents both by interference with the synthesis of deoxy-thymidine-mono-phosphate, with a compensative increase of TK1 expression, or as a measure of increased cell proliferation in the bone-marrow, after chemotherapeutic induced leukopenia." (PMID 29662653, 2018).
malignant glioma (1 paper, 2015). A grade III or grade IV glioma arising from the central nervous system. "The tomato thymidine kinase 1 (ToTK1) is a dNK that has been selected for its in vitro kinetic properties and then successfully been tested in vivo for the treatment of malignant glioma." (PMID 26061968, 2015).
malignant uterine tumors (1 paper, 2023). "Most importantly, TYMS, TK1, miR-26b-5p, and Sp1 panel should be further investigated as biomarkers of pathogenesis, prognosis, and differentiation of uLMS from other benign and malignant uterine tumors." (PMID 37373974, 2023).
monoclonal gammopathy (1 paper, 2023). A condition characterized by the abnormal presence of monoclonal immunoglobulins in the blood or urine. "There are three main groups of internal tumour markers in equine medicine: hormones, enzymes (TK1, ALP) and antibodies (monoclonal gammopathy, autologous Ig against erythrocytes or thrombocytes)." (PMID 36495211, 2023).
nevus (1 paper, 2022). Nevus (or naevus, plural nevi or naevi, from nævus, Latin for "birthmark") is the medical term for sharply circumscribed[1] and chronic lesions of the skin or mucosa. "In the meantime, an overall difference in the expression of TK1 between the primary or metastatic SKCM and nevus or normal tissue was shown (p = 0.0003)." (PMID 35311151, 2022).
Obesity (1 paper, 2021). Accumulation of substantial excess body fat. "In humans, TK1 elevation is associated with numerous comorbidities such as obesity, fatty liver, and pre‐cancerous lesions." (PMID 34359096, 2021).
oral squamous cell carcinoma (1 paper, 2025). "To investigate the potential role of TK1 in oral squamous cell carcinoma (OSCC cell motility, we further analyzed its expression in highly migratory OSCC subpopulations." (PMID 40564887, 2025).
osteoarthritis (1 paper, 2024). A noninflammatory degenerative joint disease occurring chiefly in older persons, characterized by degeneration of the articular cartilage, hypertrophy of bone at the margins and changes in the synovial membrane. "We used deep machine learning algorithms, including the LASSO and SVM algorithms, to identify four candidate feature genes in Osteoarthritis cases: TK1, CD300A, EGFR, and UTY." (PMID 38549939, 2024). "Further analysis revealed that the TK1 gene was upregulated in osteoarthritis, tenosynovial giant cell tumors, and synovial sarcoma, while the C6 gene was downregulated in these three diseases." (PMID 38549939, 2024). "Therefore, this study reveals potential shared molecular mechanisms between tenosynovial giant cell tumors and osteoarthritis, synovial sarcoma, particularly the differential expression of TK1 and C6 genes in these diseases may reveal shared pathological processes." (PMID 38549939, 2024). "Further data analysis validated that these genes (TK1, CD300A, EGFR, and UTY) are correlated with the immune microenvironment of Osteoarthritis." (PMID 38549939, 2024). "However, the roles of TK1, CD300A, and UTY in Osteoarthritis have not yet been reported." (PMID 38549939, 2024).
osteosarcoma (1 paper, 2023). A usually aggressive malignant bone-forming mesenchymal neoplasm, predominantly affecting adolescents and young adults. "The protein expression of TK1 indicates the nuclear origin of the cells did not originate from the osteosarcoma 143B(TK-) ρ0 cells as expected." (PMID 37580812, 2023). "However, after treating the resulting cells with BrdU, the cells lacked the expected resistance of the osteosarcoma 143B(TK-) ρ0 cells, which was supported by western blot showing TK1 protein expression in the resulting cells." (PMID 37580812, 2023).
pancreatic ductal adenocarcinoma (1 paper, 2022). An infiltrating adenocarcinoma that arises from the epithelial cells of the pancreas. "Silencing of TK1 decreased cell proliferation in vitro and in vivo in pancreatic ductal adenocarcinoma (PDAC) cell lines suggesting the exploitation of TK1 not just as a biomarker but also as a potential anti-cancer target." (PMID 35203388, 2022).
papillary thyroid carcinoma (1 paper, 2024). "The aim of this study was to develop a nomogram, using serum thymidine kinase 1 protein (STK1p) combined with ultrasonography parameters, to early predict central lymph node metastasis (CLNM) in patients with papillary thyroid carcinoma (PTC) pre-surgery." (PMID 38887267, 2024).